OR9A2 (olfactory receptor family 9 subfamily A member 2)
Description:
Odorant receptor.
Tractability: Antibody: UniProt places it where antibodies can reach, with medium confidence; UniProt predicts a signal peptide or a membrane-spanning region; its Gene Ontology location is reachable by antibodies, with medium confidence.
Gene: Protein-coding gene on chromosome 7 (143,026,200 to 143,027,132, reverse strand). Ensembl gene ENSG00000179468.
Subcellular location: Cell membrane
Pathways (Reactome):
Sensory Perception: Expression and translocation of olfactory receptors
Gene Ontology:
Molecular function: G protein-coupled receptor activity; olfactory receptor activity
Biological process: detection of chemical stimulus involved in sensory perception of smell; G protein-coupled receptor signaling pathway
Cellular component: membrane; plasma membrane
Genetic constraint (gnomAD): Loss-of-function variants: 14 observed, 19.64 expected, observed/expected ratio (o/e) 0.71, 90% interval 0.47 to 1.11. The upper end of that interval is the gene's LOEUF score, 1.11, which puts it in group 4 of 6, group 1 being the genes least tolerant of losing a copy. Missense variants: 353 observed, 390.59 expected, observed/expected ratio (o/e) 0.9, 90% interval 0.83 to 0.99. Synonymous variants: 142 observed, 151.18 expected, observed/expected ratio (o/e) 0.94, 90% interval 0.82 to 1.08.
Homologues: Orthologues: pig OR9A2 (84% identical), rat Or9a2 (82% identical), mouse Or9a2 (82% identical), dog OR9A2 (79% identical), guinea pig OR9A2 (73% identical). Paralogues in human: OR9A4 (77% identical), OR9A1P (73% identical), OR11G2 (39% identical), OR11H4 (37% identical), OR11H6 (37% identical), OR10X1 (36% identical), OR11H7 (35% identical), OR11H12 (35% identical), OR11H1 (35% identical), OR11H2 (35% identical), OR9G1 (35% identical), OR11A1 (35% identical), and 21 more.